NOTCH1 (notch receptor 1)
Diseases named in the same sentence as NOTCH1 in open-access papers (continued):
Sharing a sentence is not in itself a finding about the gene and the disease.
tumor (continued). "In addition to FLNa, PrPC interacts with Notch1, forming a PrPC/FLNa/Notch1 complex, which is associated with enhanced PDAC proliferation, invasiveness, and xenograft tumor growth." (PMID 33418999, 2021). "Interestingly, ALDH1A1+ BCSCs that co-expressed Notch1 showed direct contact with the tumor endothelium that expressed DLL4 in a tumor arteriole." (PMID 34168243, 2021). "Conversely, Notch1 expression is observed in tumor tissue only." (PMID 33804511, 2021). "JAG1, Notch1 and Slug expression correlate in patient tumour samples." (PMID 34295896, 2021). "Of note, alterations of NOTCH1 in cancer can both be oncogenic or imply loss of function depending on the context, but NOTCH1 mutations in HNSCC are generally considered as loss of function mutations and therefore NOTCH1 acts as tumor suppressor." (PMID 34204886, 2021). "NOTCH1 is reported to have a bimodal role as a tumor suppressor and an oncogene in several cancers." (PMID 33407425, 2021). "Furthermore, ablation of Pin1 reduced the expression levels of Notch1/4, thus eliciting sensitivity to chemotherapeutic drugs and inhibiting tumor growth and metastatic spread in vivo." (PMID 35582386, 2021). "In addition, loss of function of NOTCH1 suppresses HER3 expression through increased phosphorylation of serine 473 of AKT in SCCHN cells, and promotes the aggressiveness of the tumor cells." (PMID 34465724, 2021). "Compared with non-tumor tissues, NOTCH1 was highly expressed in PC tissues and positively correlated with short-term survival, whereas knockdown of NOTCH1 inhibited cell proliferation and induced G1 cell cycle arrest, apoptosis, metastasis, and gemcitabine resistance in PC." (PMID 34341330, 2021). "Our in vivo study clearly showed that overexpression of miR-221/222 significantly enhanced tumor growth, providing an evidence to target miR-221/222 as an upstream regulator of Notch1 signaling in regulating CSCs and achieving potential therapeutic effects on NSCLC." (PMID 33959615, 2021). "Our data suggests that NOTCH1 inhibition might be used to slow down tumor growth but should be avoided in combination with cytotoxic therapies due to the induction of tumor cell networks." (PMID 33579922, 2021). "Moreover, Notch1 directly promotes the expression of many key glycolytic genes that facilitates aerobic glycolysis and tumor growth." (PMID 34482375, 2021). "An increase in flux to proteoglycan synthesis could globally support the expression of cell surface receptors and tumor promoters such as Notch1." (PMID 34548906, 2021). "Furthermore, the decrease in FBXW7 transcriptional activity was found to promote tumor angiogenesis, observed through enhanced expression of angiogenic driver proteins, including NOTCH1." (PMID 33822486, 2021). "Supportively, data from preclinical mice model with implantation of H1299 cells also demonstrated that knock‐down of circNOTCH1 could block GPER‐induced NOTCH1 to suppress NSCLC tumour growth." (PMID 33237585, 2021). "Wang and colleagues revealed IL17A promoted tumor progression via STAT3/NF-κB/Notch1 pathway." (PMID 34122408, 2021). "The loss-of-function mutations in Notch1 located mainly to the extracellular domain with no specific domain preference and show that Notch signaling acts as a tumor suppressor in SCLC." (PMID 34572582, 2021). "The expression of ADAM10, Notch1, Notch2, Notch3, Notch4, Hey1, vimentin and N‐cadherin at the transcript level was significantly upregulated, whereas transcripts of E‐cadherin significantly decreased in tumour tissues versus in normal liver tissues of HCC." (PMID 33955149, 2021). "GNA14 regulated the RB pathway by promoting Notch1 cleavage to inhibit tumor proliferation, and might inhibit tumor metastasis by inhibiting the expression of JMJD6." (PMID 33500727, 2021).
tumor (continued). "Activating mutations within and surrounding the PEST domain of Notch1, 2, and 3; mutations disrupting the NRR and heterodimerisation domains; and focal amplifications have been identified in patient tumours and patient-derived xenograft (PDX) models, notably with enrichment in TNBCs." (PMID 34295896, 2021). "In addition, both BXL0124 (a Gemini vitamin D analog) and paeoniflorin (a major active ingredient in Chinese peony) can block tumor cell proliferation by inhibiting Notch1 activation." (PMID 34374886, 2021). "The study demonstrated that knockdown of Notch-1 could partially restore the sensitivity to regorafenib and inhibit cell growth, indicating that Notch-1 may play a role in tumour resistance." (PMID 34733591, 2021). "Indeed, the majority of patients suffered from gastrointestinal toxicity, due to the simultaneous blockade of Notch1 and Notch2 receptors and to the inhibition of Notch signaling in non-tumor tissues." (PMID 33804511, 2021). "However, it is evident that the frequency of NOTCH1 mutations and Notch pathway activation is different in HPV− and HPV+ tumours." (PMID 34944837, 2021). "Conversely, high levels of Notch1 underlaid SCLC chemoresistance to doxorubicin that was resolved by Notch1 knockdown, which once again points out the controversial role of Notch signaling in tumor onset and progression." (PMID 34680255, 2021). "It was further reported that high expression levels of NOTCH1 mRNA in the tumour tissues correlate with improved patient outcomes and longer survival, which seemed to corroborate a positive, tumour-suppressor-like function of the Notch pathway, which is then lost by alterations." (PMID 34944837, 2021). "In MTC, overexpression of Notch1 and Notch3 may limit tumor cell growth and proliferation in vitro and in vivo in a dose-dependent manner." (PMID 33681228, 2021). "First, we showed that DLL4 was a potent stimulator of Notch1 signaling mainly in NOTCH1-mutated CLL cells, leading to the activation of some protumor genes and inducing processes that confer aggressiveness to the tumor, such as cell proliferation, migration, and angiogenesis." (PMID 31616059, 2020). "The aim of this study was to determine the protein expression levels of Notch1, Hes1,Ascl1, DLL3 in SCLC tumor specimen and the potential association of these biomarkersto platinum chemotherapy sensitivity, prognosis as well as clinical factors in SCLCpatients." (PMID 33104707, 2020). "Our previous studies have found that SKOV3 could promote immune escape and tumor progression via Notch1 pathway." (PMID 32547317, 2020). "We noticed that, compared with the IgG control group, anti-Notch1 or Avastin treatment reduced the tumor volume and weight by 20–60%, while strong inhibition of tumor growth was achieved by anti-Notch1 and Avastin combinatorial treatment, with over 80% antitumor efficacy." (PMID 33046710, 2020). "Moreover, the combination of PF-03084014 and fludarabine is able to reduce angiogenesis and CXCL12-induced responses in NOTCH1-mutated CLL cells, in particular those related to tumor migration and invasion." (PMID 31616059, 2020). "A lot of studies have provided data on the role of the Notch1 in the development of tumor." (PMID 32547317, 2020). "Thus, we evaluated the expressions of Notch-1 and Notch-2 to further explore the molecular mechanism by which the 3D microenvironment in MC-B hydrogels regulates tumor aggressiveness in OC." (PMID 33003514, 2020). "In conclusion, HOAX-AS3 inhibition may suppress tumor progression and enhance sensitivity to cisplatin in BC via modulation of the miR-455-5p-Notch1 axis." (PMID 33643896, 2020).
tumor (continued). "Among all 169 potential cancer drivers, 33 genes, including Notch1, Jup and Met, showed oncogenic features, whereas the majority of genes, including Lipc, Cntn5, Hdac4, Nrxn3 and Cntnap5c, exhibited tumour suppressor features." (PMID 32591500, 2020). "This may help to explain the dual functions of NOTCH1 as a tumour suppressor and an oncogene under different circumstances." (PMID 32591500, 2020). "Elevated Notch1 pathway activity inhibits the function of CAFs in promoting tumor progression." (PMID 33109684, 2020). "Among them, there could be potential tumor suppressors that NOTCH1 needs to dampen to exert its oncogenic function." (PMID 32708470, 2020). "Finally, in order to investigate the clinical significance of our findings, we first analysed data from the public database The Human Protein Atlas to determine the protein abundance of DYRK2 and NOTCH1 in tumour tissues." (PMID 31605148, 2020). "Hence, these previous results generated from tumor models are also consistent with data derived from wound healing models in terms of the role of Notch1 pathway in determining function and cellular activity of fibroblasts." (PMID 33109684, 2020). "The data showing the correlation in the levels of both proteins in tumour tissue agree with our in vitro data and suggest that the degradation of Notch1-IC by DYRK2 might also be relevant in cancer patients." (PMID 31605148, 2020). "Furthermore, we conducted in vivo treatment of TM00091 PDX tumours, which carry two BRCA1 point mutations (Q356R and C61G), with NOTCH1 hyperactivation." (PMID 32591500, 2020). "However, Notch-2, Jagged-1, Hey-1, and Hey-2 were overexpressed in OS tumor biopsy specimens, while Notch-1 and DLL1 were decreased in these specimens." (PMID 33411691, 2020). "The expression of Notch-1, Jagged-1, Hes-1 and Hey-2 was upregulated in OS tumor tissues." (PMID 33411691, 2020). "Notch-1 and survivin are associated with GBM apoptosis and proliferation in tumor microenvironment." (PMID 32998285, 2020). "For example, in basal kerantinocytes, uPAR may sequester the TNF-α converting enzyme (TACE) within lipid rafts, preventing Notch1 activation, and thereby promoting cell proliferation and tumor formation." (PMID 33255171, 2020). "We next explored the expression of Notch-1 in the tumor tissues among these groups." (PMID 32586404, 2020). "Overall, these results imply that treating cancer patients with antiangiogenic therapy combined with anti-Notch1 might reduce cancer risk, which is achieved by inhibition of either CSC properties or tumor angiogenesis." (PMID 33046710, 2020). "Given the small percentage of tumor cells with NOTCH1 activation in samples with the peripheral pattern, it is unlikely that any RNA expression analysis of whole tumor lysates could identify this subset." (PMID 33322834, 2020). "Notch1 is known to regulate the crosstalk between different cells in the tumour microenvironment." (PMID 33168804, 2020). "In particular, miR-29 has been reported to function as a tumor suppressor in a NOTCH1-driven T-ALL model and found to be significantly downregulated in T-ALL samples relative to normal thymocytes through the regulation of key genes involved in epigenetic regulatory mechanisms." (PMID 32708470, 2020). "It is plausible that these regulations may affect T-ALL cell growth in vivo, where the tumor microenvironment, in concert with NOTCH1 signaling, is a critical factor for tumor establishment and growth." (PMID 32708470, 2020). "In addition, IL-6 activities in BC were found to be mediated through activation of the bromodomain and extraterminal (BET) protein BRD4 that was required for Notch1-mediated pro-tumor activities." (PMID 32605277, 2020). "Additionally, manipulation of NOTCH signaling in NOTCH1 mutant HNSCC cell lines demonstrates that it functions as a tumor suppressor in vitro and in vivo." (PMID 33322834, 2020).
tumor (continued). "Likewise, flow-cytometric analysis also suggested an increased percentage of CD4−CD8−CD25+CD44+Ikaros+ cells and a downregulation in CD4−CD8−CD25+CD44+Notch1+ cells within the thymus of tumor-bearing vs. control mice (Figure 4D1)." (PMID 32582141, 2020). "To determine whether RP11-59H7.3 triggers tumor-enhancing roles in CRC by controlling the miR-139-5p/NOTCH1 axis, we examined the effects of NOTCH1 and miR-139-5p on RP11-59H7.3-induced cell invasion and movement." (PMID 32507766, 2020). "Ultimately, NOTCH1 triggers a program of genes involved in early differentiation that may have different phenotypic consequences depending on a tumor’s genetic background." (PMID 33322834, 2020). "In addition, in several researches, its tumor suppressive role on NOTCH1 (apoptosis induction and proliferation inhibition) and c-Myc/CCND1 (G1 arrest) has been reported." (PMID 32440325, 2020). "Intriguingly, in the progress of cancer, Notch1 might act as either an oncogene or a tumor suppressor gene depending on the type, stage and histotypic categories of tumor." (PMID 32123166, 2020). "Abnormal activation of Notch1 is relatively common in many tumor types." (PMID 33344242, 2020). "Of 138 insertion sites identified in 108 Notch1-trapped SB tumours, 136 (98.6%) were concentrated between exon 25 and exon 30, and 73.5% (100/136) were in the same direction as the direction of gene expression, indicating that the transposon specifically inserted to result in overexpression of ICN1." (PMID 32591500, 2020). "KLF2 acts as a tumor suppressor in CRC via regulating HIF-1α/Notch-1 signaling pathway." (PMID 32523679, 2020). "By hyperactivating Notch-1 in the vessels, ponatinib exerts an “on-target off tumor effect”, which leads to deleterious effects and may explain the drug’s vasculotoxicity." (PMID 32197359, 2020). "TNBC and basal tumour incidence markedly increased with increasing NOTCH1 expression." (PMID 32591500, 2020). "This allows us a novel pathway through which to target the oncogenic activity of Notch1 in the GBM—a pathway that is much more targeted to tumor cells and therefore, may be much less likely to be toxic to patients." (PMID 33255632, 2020). "Whether NOTCH1 signaling promotes or suppresses tumor formation, progression, and metastasis for various HNSCC types is an open question." (PMID 33322834, 2020). "Taken together, NOTCH1 likely has a tumor suppressor function in a wide range of SCCs." (PMID 33322834, 2020). "In particular, some of the most significant genes according to our approach, like FUBP1, NOTCH1, PTEN, EGFR, and NF1, were mutated in less than 10% of the patients within that tumor type, indicating that mutations in these genes are strongly associated with global changes in expression." (PMID 32732999, 2020). "Transcriptional profiling reveals that epithelial NOTCH1 signaling creates a tumor microenvironment (TME) reminiscent of poorly prognostic human CRC subtypes (CMS4 and CRIS-B), and drives metastasis through transforming growth factor (TGF) β-dependent neutrophil recruitment." (PMID 31526760, 2019). "Our data support the suggested dual oncogenic and tumour suppressive role for NOTCH1 in HNSCC." (PMID 31427592, 2019). "We confirmed that GFP+ cells expressed high levels of GFP, Notch1, Nrarp, Hes1 and Olfm4, the three-latter representing direct Notch targets, indicating that the Notch pathway is indeed active in Notch1+ tumour cells." (PMID 30696875, 2019). "In addition, TECs frequently express elevated Notch1 in human tumor tissues, including melanoma, breast carcinoma, lung adenocarcinoma, serous ovarian carcinoma, and colorectal carcinoma, and this expression correlates with poor prognosis." (PMID 31600937, 2019). "Both the high expression of Notch1 and RNF187 were associated with aggressive tumor behavior." (PMID 31477177, 2019). "Orthotopic xenograft tumor model revealed that Notch1 knockdown inhibited tumor metastasis in vivo." (PMID 31477177, 2019).
tumor (continued). "NOTCH1 was previously identified as a direct target of miR-34a in tumor cells." (PMID 31215466, 2019). "Compared to other tumors, Notch1 in GBM has a much higher Tumor/Normal tissues ratio." (PMID 31382985, 2019). "Overexpression of Notch1 in a human pNET cell-line (BON cells) using an inducible construct demonstrated the suppression of tumor growth, an increase in the downstream target of the Notch1 Hes, a decrease in NET marker ASCL1, and inhibition of neuroendocrine differentiation." (PMID 31739580, 2019). "Notch1-expressing cells represent thus genuine CSCs in both genetic and carcinogenic tumour models." (PMID 30696875, 2019). "The expression of Notch1 in tumor tissue was localized to distinct parts of differentiation." (PMID 31018488, 2019). "In the forest map, the 95% CI of the OR was on the right side of the vertical line (Z = 2.99, P = 0.003 in the overall effect test), which indicated that upregulation of Notch1 signaling may promote tumor enlargement in PTC." (PMID 30622441, 2019). "Thus, we firstly screened Notch1 and Notch2 mRNA expressions in tumor and peritumor tissues which were obtained during gastroscopic biopsy in 24 of GC patients (7 of TNM stage I, 6 of stage II, 6 of stage III, and 5 of stage IV)." (PMID 30988066, 2019). "Altogether, the results point to a functional axis of DLL4/DLL1 and Notch1/Notch2 as an essential element in DC-T-cell interactions needed for the induction of effector T-cell differentiation and eliciting T-cell-mediated anti-tumor immunity." (PMID 30940183, 2019). "Additionally, positive correlations were found between Notch1 signaling and tumor size (OR = 4.34, 95% CI 1.66–11.38, P = 0.003), capsular invasion (OR = 3.49, 95% CI 1.90–6.41, P < 0.0001) and clinical stage of PTC (OR = 2.31, 95% CI 1.05–5.11, P = 0.04)." (PMID 30622441, 2019). "In addition, Notch1 has been reported to play a bimodal role as a tumour promoter and tumour suppressor." (PMID 30970654, 2019). "Additionally, inhibition of NOTCH1 or HEY1 significantly decreased cell growth of primary tumor-derived cells, indicating their potential involvement in HNSCC development." (PMID 31597699, 2019). "Moreover, the findings obtained with DAPT were recapitulated when Notch1 was knocked-down in the tumor cells by siRNA; in these experiments, Notch1 siRNA has led to similar reduction in TNFα-induced contact-dependent induction of CXCL8 as did DAPT." (PMID 31105691, 2019). "In addition, the tumor also had genomic alterations in NOTCH1 L2457V (designated as a benign genomic alteration in ClinVar) and NOD1 L475fs*35." (PMID 31362756, 2019). "Notably, this increased in vivo tumor growth is determined by the increase in cytokines secretion and Notch1 activation, thus suggesting a compensatory response of cancer cell." (PMID 31379945, 2019). "Taken together, the results from our meta-analysis suggest that PTC patients with higher Notch1 signaling activity may tend to have more tumor invasiveness." (PMID 30622441, 2019). "In addition, the authors demonstrated an opposite expression of Notch1 and Notch2 proteins during tumor development, related to its differentiation state." (PMID 31379945, 2019). "In addition to filamin A, PrPc interacts with Notch1, forming a PrPc/FLNA/Notch1 complex, which is associated with enhanced PDAC proliferation, invasiveness, and xenograft tumor growth." (PMID 31618844, 2019). "Also, in the context of TNFα stimulation, p65 activation that led to elevated Notch1 activation took place mainly in the tumor cells but also in the MSCs." (PMID 31105691, 2019).